HMGB1 (high mobility group box 1)
Diseases named in the same sentence as HMGB1 in open-access papers (continued):
Sharing a sentence is not in itself a finding about the gene and the disease.
anaphylaxis (1 paper, 2022). An acute hypersensitivity reaction that occurs from exposure to an allergen. "It is noteworthy that the agents currently used for clinical treatment of anaphylaxis, adrenaline and noradrenaline, efficiently inhibited the nuclear translocation of HMGB1 induced by histamine in the present study." (PMID 36275732, 2022). "Adrenaline and noradrenaline, which are commonly used in the clinical treatment of anaphylactic shock, also inhibited the histamine-induced HMGB1 translocation in endothelial cells." (PMID 36275732, 2022). "Anti-HMGB1 therapy may provide a novel treatment for life-threatening systemic anaphylaxis." (PMID 36275732, 2022).
anterior uveitis (1 paper, 2016). Inflammation of the iris and anterior chamber of the eye. "The serum HMGB1 of AS patients was significantly higher than in healthy controls and positively correlated with BASDAI, BASFI, ASDAS-ESR, ASDAS-CRP, ESR, and CRP, but not with HLA-B27, anterior uveitis, and recurrent diarrhea." (PMID 27800496, 2016).
anxiety disorder (1 paper, 2024). A category of psychiatric disorders which are characterized by anxious feelings or fear often accompanied by physical symptoms associated with anxiety. "We investigated whether comorbid mood and anxiety disorders influence the effect of CI on plasma concentrations of HMGB1, RAGE, ROS/RNS, ApoD, and NRF2 in AUD patients." (PMID 38535924, 2024).
astrocytomas (1 paper, 2024). "Based on similarities between HMGB1 and HMGB2, we hypothesize that astrocytomas with high HMGB2 expression have a more powerful immune response to damage-associated molecular patterns (DAMPs), arising after RT plus temozolomide and/or oncolytic viral vectors injection." (PMID 38672598, 2024).
autonomic dysfunction (1 paper, 2026). "Elevated HMGB1 was also associated with an increased probability of autonomic dysfunction (RR = 2.15, 95% CI 1.07-4.33, p=0.015)." (PMID 42199430, 2026).
babesiosis (1 paper, 2017). Babesiosis refers to a condition caused by microscopic parasites that infect the red blood cells. "In this study, concentrations of plasma HMGB-1 were increased in dogs with babesiosis compared to healthy dogs at admission, as well as on day 6 after treatment." (PMID 28363279, 2017). "Markers for endothelial activation, such as TM and HMGB1, were significantly increased in dogs with complicated babesiosis at admission compared to day 6, while compared to dogs with uncomplicated babesiosis VCAM-1 was increased." (PMID 28363279, 2017). "Dogs with complicated babesiosis had higher concentrations of TM, HMGB1 and TAFI at admission compared to the 6th day." (PMID 28363279, 2017). "Thus, the study suggests that HMGB1 activates components necessary for recruitment, adhesion, and transmigration of leukocytes across an activated endothelium in babesiosis." (PMID 28363279, 2017). "Markers for endothelial activation, such as TM, HMGB-1 and VCAM-1, were significantly increased in dogs with babesiosis at admission compared to healthy dogs." (PMID 28363279, 2017). "Dogs with babesiosis also had increased concentrations of TM, ICAM-1 and HMGB-1 and decreased plasminogen and PAI-1 at presentation compared to day 6 after treatment." (PMID 28363279, 2017). "Concentrations of TM, HMGB-1, VCAM-1 and suPAR were increased in dogs with babesiosis at admission compared to healthy dogs." (PMID 28363279, 2017).
Behcet disease (1 paper, 2018). A chronic, relapsing, multisystemic vasculitis characterized by mucocutaneous lesions, as well as articular, vascular, ocular and central nervous system manifestations. "Neutrophils help drive Behcet's disease, and expression of proinflammatory cytokines such as TNF-α, IFN-γ, and IL-6 in neutrophils is enhanced by extracellular HMGB1, which acts via the NF-κB pathway." (PMID 30473885, 2018).
benign prostatic hyperplasia (1 paper, 2019). A non-cancerous nodular enlargement of the prostate gland. "Furthermore, IHC of 64 paraffin- embedded human PCa tissues and 14 benign prostatic hyperplasia (BPH) or normal prostate samples showed that expression of both HMGB1 (P = 0.008) and BRG1 (P = 0.045) was dramatically increased in PCa tumors than the corresponding BPH tissues." (PMID 31410208, 2019).
biliary tract cancer (1 paper, 2019). "Moreover, there are some reports of HMGB1 in biliary tract cancers." (PMID 31399104, 2019).
Bradycardia (1 paper, 2020). A slower than normal heart rate (in adults, slower than 60 beats per minute). "Furthermore, the frequency of the calcium signal in CM was significant reduced in the presence of histones, as well as after incubation with HMGB-1, which was associated with bradycardia of the CMs in vitro." (PMID 32403440, 2020).
bronchopulmonary dysplasia (1 paper, 2023). Bronchopulmonary dysplasia is a chronic respiratory disease that results from complications related to lung injury during the treatment of infant acute respiratory distress syndrome in low-birth-weight premature infants or from abnormal lung development in older infants. "HMGB-1 levels are persistently elevated in bronchopulmonary dysplasia (BPD), which affects the long-term prognosis of extremely preterm infants, and HRG may be indirectly involved in the pathogenesis of BPD in extremely preterm infants." (PMID 36672720, 2023).
cerebellar degeneration (1 paper, 2014). Degeneration of the cerebellum. "Because complete elimination of HSPA5 in Purkinje cells leads to reduced cytosolic ubiquitination and accelerated cerebellar degeneration in a mouse model, HMGB1 could be a target of mutant TBP in SCA17, as well as NFYA." (PMID 25549101, 2014).
cerebral lesions (1 paper, 2017). "They further indicated that increased HMGB1 levels have incoherent correlation with infarct size and location, since higher HMGB1 levels are observed in patients with more severe cerebral lesions." (PMID 29054968, 2017).
chlamydial infection (1 paper, 2008). "HMGB1 release was evaluated 24 h, 48 h and 72 hpi and chlamydial infection morphology was followed using confocal laser scanning microscopy." (PMID 18284660, 2008).
cholangiomas (1 paper, 2023). "HMGB1 and IL-6 can regulate the occurrence of biliary proliferation, atypical hyperplasia, cholangiomas, and CCA." (PMID 37347224, 2023).
cholangitis (1 paper, 2025). An acute or chronic inflammatory process affecting the biliary tract. "The results of the study showed that high expression of HMGB1 was associated with MVD and poor prognosis in clinical analysation andpostoperative serum HMGB1 and cholangitis could predict high recurrence and unfavourable prognosis." (PMID 39904827, 2025).
chronic allograft nephropathy (1 paper, 2021). "A positive association between HMGB1 and TGF-β1 expression was identified in chronic allograft nephropathy." (PMID 33777037, 2021).
clear-cell ovarian carcinomas (1 paper, 2020). "HMGB1 immunostaining in serous, mucinous, endometrioid, and clear-cell ovarian carcinomas shows that HMGB1 expression is observed in different EOC histotypes." (PMID 32867128, 2020).
coagulation abnormalities (1 paper, 2009). "Patients with clinically significant coagulation abnormalities (international nationalized ratio (INR) >1.5) had significantly higher plasma levels of HMGB1 (P = 0.01)." (PMID 19887013, 2009).
cocaine addiction (1 paper, 2024). "As synthetic HMGB1 fragments that specifically interfere with HMGB1–RAGE signaling after CPP training sessions could attenuate cocaine‐induced CPP, targeting HMGB1–RAGE signaling pathway might be an effective approach to ameliorate cocaine addiction." (PMID 38450910, 2024). "Our previous study demonstrates that intracellular HMGB1 regulates the formation of cocaine‐related memory by binding to glutamate receptor, however, whether the secretion of neural HMGB1 acts on microglia or contributes to cocaine addiction is largely unknown." (PMID 38450910, 2024). "However, whether the secretion of HMGB1 acts on microglia or contributes to cocaine addiction is largely unknown." (PMID 38450910, 2024). "Therefore, therapeutic strategies targeting HMGB1 signaling, especially the HMGB1–RAGE axis, may be an effective approach to prevent the cocaine addiction." (PMID 38450910, 2024).
cognitive (1 paper, 2024). "TLB:Improves cognitive deficits in both animal models.Ameliorates neuroinflammation and oxidative stress by inhibiting the HMGB1/TLR4/NF-κB signaling pathway and activating the SIRT3/SOD2 pathway, which helps to restore redox homeostasis and suppress neuroinflammation." (PMID 39459209, 2024).
condyloma acuminatum (1 paper, 2014). "The present study investigated the HMGB1, TLR4 and nuclear factor-κB p65 expression in condyloma acuminatum (CA) and verruca vulgaris (VV)." (PMID 25118798, 2014).
corneal disease (1 paper, 2022). "In contrast, in the mTLR4KO and their WT littermates, GLY significantly reduced corneal disease, TLR4, TLR9, HMGB1, and RAGE corneal mRNA expression after infection." (PMID 36422579, 2022).
Corneal opacity (1 paper, 2022). A reduction of corneal clarity. "To investigate the related signaling pathways through which HMGB1 generates corneal opacity, we used immunohistochemical staining for TGF-β1, Fibronectin, α-SMA and Collagen III in corneal tissue at 28 days after alkali-burn." (PMID 35586052, 2022).
coronary aneurysm (1 paper, 2020). Abnormal balloon- or sac-like dilatation in the wall of coronary vessels. "Therefore, the clinical treatment of KD with active anti-inflammatory, anticoagulant, high-dose gamma globulin infusion, etc., can also block the secretion of HMGB1 at an early stage to prevent coronary artery injury and reduce the occurrence of coronary aneurysms." (PMID 32183905, 2020).
Crush Syndrome (1 paper, 2016). Severe systemic manifestation of trauma and ischemia involving soft tissues, principally skeletal muscle, due to prolonged severe crushing. "We found that HMGB1 was dramatically increased in crush syndrome, which could be partially corrected by treatment with Ani." (PMID 27065867, 2016). "However, neutralization of HMGB1 with its antibody had no influence on the effect of Ani on on-site mortality in mice with crush syndrome (data not shown)." (PMID 27065867, 2016).
Dengue hemorrhagic fever (1 paper, 2022). A serious condition caused by Dengue virus infection. "For instance, extracellular HMGB1 was related to the pathogenesis of dengue hemorrhagic fever-dengue shock syndrome (DHF/DSS), presumably through the vascular barrier disruption." (PMID 35058496, 2022).
dental caries (1 paper, 2014). The decay of a tooth, in which it becomes softened, discolored, and/or porous. "Our results indicated that HMGB1 may be involved in the inflammatory response of teeth to bacteria in dental caries and that odontoblasts act as essential HMGB1-secretory cells in inflamed dental pulp tissues." (PMID 25114379, 2014).
dilatation (1 paper, 2024). "In this study, significantly higher levels of HMGB1 mRNA in the PBMCs of patients six months after MI were found in patients with adverse LV remodeling, severe LV dilatation, impaired LV systolic function, and LV enlargement." (PMID 39457420, 2024).
Dystrophic epidermolysis bullosa (1 paper, 2021). "Moreover, HMGB1 peptide is being evaluated in clinical trials in Japan (S-005151, Redasemtide) for dystrophic epidermolysis bullosa (phase II) and acute ischemic stroke (phase II)." (PMID 34565478, 2021).
eczema (1 paper, 2020). "Though no study has examined if RAGE specifically participates in pathophysiology of eczema in children, HMGB1, a main ligand in the RAGE inflammatory axis, has been shown to be significantly higher in children with eczema and its level is related to the severity of clinical disease." (PMID 32846877, 2020).
enteritis (1 paper, 2021). Inflammation of the small intestine. "In previous studies, GL could reduce the serum levels of inflammatory cytokines and HMGB1 after radiation exposure, resulting in ameliolating radiation-induced enteritis and radiation-induced lung injury." (PMID 34526618, 2021).
enteropathy (1 paper, 2020). "In NSAIDs-induced enteropathy, the prominent cytoplasmic staining of HMGB1 in damaged epithelial cells was observed and recombinant HMGB1 aggravated the damage through the activation of NF-κB and mitogen-activated protein kinases." (PMID 31865463, 2020).
enterovirus infections (1 paper, 2023). "Moreover, HMGB1 was also demonstrated to exert a certain role in other enterovirus infections." (PMID 37559147, 2023).
enthesitis-related arthritis (1 paper, 2021). "Serum HMGB1 levels at the first visit were significantly elevated in children with systemic JIA compared with other groups, and so were in enthesitis-related arthritis versus healthy controls." (PMID 34247641, 2021).
Epithelial Ovary Cancer (1 paper, 2020). "Considering the relevance of HMGB proteins in Epithelial Ovary Cancer (EOC), we have determined for the first time the interactome of HMGB1 and HMGB2 related to this gynecological cancer." (PMID 32867128, 2020).
erectile dysfunction (1 paper, 2025). Persistent or recurrent inability to achieve or to maintain an erection during sexual activity. "K-Hcy promotes HMGB1/2 nuclear-to-cytoplasmic translocation, extracellular release, and subsequent SASP amplification, thereby accelerating endothelial senescence in the corpus cavernosum and contributing to erectile dysfunction in middle-aged and elderly individuals." (PMID 41281764, 2025).
erysipelas (1 paper, 2014). An infection of the upper layers of the skin caused by species of streptococcus. "HMGB1 was detected in all analyzed biopsies (11 erysipelas and 25 severe STIs) and demonstrated both a diffuse, supposedly secreted HMGB1, as well as distinct intracellular staining (evident in some but not all cells)." (PMID 24524027, 2014). "Importantly, semiquantitative assessment of HMGB1 at the infected site in patients with erysipelas compared to severe STIs revealed an increase in parallel to disease severity (p = 0.0023)." (PMID 24524027, 2014).
esophageal tumor (1 paper, 2022). "HMGB1 and RAGE revealed typically stronger staining intensity patterns in the esophageal tumor tissues of the ESCC group than the adjacent tissue group." (PMID 35829833, 2022).
esophageal ulcerations (1 paper, 2024). "Carbenoxolone, an aglycone derivative of Gly and another reported HMGB1 binder, has been utilized for ameliorating inflammation, peptic, and esophageal ulcerations." (PMID 39682695, 2024).
Flavivirus Infections (1 paper, 2018). Infections with viruses of the genus FLAVIVIRUS, family FLAVIVIRIDAE. "HMGB1 signaling has been implicated in flavivirus infection, particularly DENV68,69." (PMID 29880853, 2018). "However, although induction of HMGB1 signaling is consistent with flavivirus infections, its functional role in context of ZIKV-infected hSeC remains to be determined." (PMID 29880853, 2018).
focal and segmental glomerulosclerosis (1 paper, 2022). "TGFβ-1 seems to be directly upregulated by HMGB1-triggered routes, and there is supporting evidence of elevated urinary levels of TGFβ-1 in children with idiopathic nephrotic syndrome and in focal and segmental glomerulosclerosis (FSGS)." (PMID 36551967, 2022).
focal epilepsy (1 paper, 2014). A seizure caused by a localized disorder. "The purpose of the present study was to investigate the role of interleukin-1β (IL-1β) and high mobility group B1 (HMGB1) in the generation of seizure-like discharges using two models of focal epilepsy in a rat entorhinal cortex slice preparation." (PMID 24936172, 2014).
fungal keratitis (1 paper, 2024). "HMGB1 is a promising and significant therapeutic target for the management of bacterial and fungal keratitis, as it plays a crucial role in influencing inflammatory factors." (PMID 38655086, 2024).
glomerulosclerosis (1 paper, 2024). A hardening of the kidney glomerulus caused by scarring of the blood vessels. "First, HMGB1 promotes renal inflammation by recruiting immune cells and activating the nuclear factor-kB pathway, which in turn mediates the apoptosis of glomerular cells and deposition of the mesangial matrix, thereby aggravating proteinuria and glomerulosclerosis." (PMID 38481996, 2024).
gram-positive bacterial infections (1 paper, 2020). Infections caused by bacteria that retain the crystal violet stain (positive) when treated by the gram-staining method. "Caspase-11 is not activated in gram-positive bacterial infections, and caspase-11 activation results in the secretion of IL-1α and specific high-mobility group box-1 (HMGB1), triggering direct pyroptosis." (PMID 33584697, 2020).
H1N1 virus infection (1 paper, 2025). "Indeed, H1N1 virus infection induced HMGB1 release in LET1 cells in a dose- and time-dependent manner." (PMID 39811662, 2025).
Heat Stroke (1 paper, 2025). A condition caused by the failure of body to dissipate heat in an excessively hot environment or during PHYSICAL EXERTION in a hot environment. "Research indicates that the high mobility group box-1 protein (HMGB1) signaling is activated during heat stroke, leading to cell pyroptosis." (PMID 40703654, 2025). "Elevated levels of HMGB1 are consistently observed in patients with heat stroke who exhibit significantly higher mortality rates." (PMID 40703654, 2025). "In patients or animal models of heat stroke, elevated levels of HMGB1, extracellular histone H3, and circulating heat shock proteins (e.g., HSP70) have been observed in plasma." (PMID 40703654, 2025).
hepatic granuloma (1 paper, 2022). A granuloma located in the liver. "Following the formation of hepatic granulomas induced by chronic schistosomiasis, HMGB1 is released from stressed or activated cells and exhibits pleiotropic functions in hepatic inflammation and fibrosis." (PMID 35335612, 2022).
Hepatic hemangioma (1 paper, 2025). A congenital vascular malformation in the liver composed of masses of blood vessels that are atypical or irregular in arrangement and size. "Treatment with hemopexin or the HMGB1 inhibitor glycyrrhizin reversed heme-induced SIRS after RFA of hepatic hemangioma in mice." (PMID 41280917, 2025). "Therefore, heme-mediated endothelial cell pyroptosis induces SIRS through the ROS/HMGB1/NLRP3 pathway after RFA of hepatic hemangiomas." (PMID 41280917, 2025). "The present study aimed to investigate whether heme-induced SIRS occurs through an HMGB1-dependent pathway in endothelial cells following RFA for hepatic hemangioma." (PMID 41280917, 2025). "In addition, hemopexin and glycyrrhizin were used to investigate the impact of HMGB1 on heme-induced SIRS post-RFA in hepatic hemangioma mice." (PMID 41280917, 2025). "In summary, these findings indicate that targeting heme or HMGB1 could alleviate SIRS after RFA of hepatic hemangiomas in mice." (PMID 41280917, 2025). "Our findings revealed that heme-induced HMGB1 upregulation leads to endothelial cell pyroptosis, resulting in SIRS following RFA of hepatic hemangioma." (PMID 41280917, 2025). "This study revealed that heme regulates HMGB1 expression and induces SIRS after RFA of hepatic hemangiomas through ROS." (PMID 41280917, 2025). "The role of high-mobility group box 1 (HMGB1) in endothelial cell pyroptosis and SIRS induction following RFA in hepatic hemangiomas remains unexplored." (PMID 41280917, 2025). "However, whether HMGB1 participates in heme-induced endothelial cell pyroptosis and SIRS after RFA in hepatic hemangiomas remains unexplored." (PMID 41280917, 2025). "In addition, our study indicates that hemopexin, a heme scavenger, and glycyrrhizin, a HMGB1 inhibitor, could alleviate SIRS after RFA of hepatic hemangioma." (PMID 41280917, 2025).
hyperandrogenism (1 paper, 2023). Excessive secretion of androgens from the adrenal glands or gonads. "None of the clinical elements used for the diagnosis of PCOS, based on the Rotterdam criteria (i.e. hyperandrogenism, oligo-anovulation and polycystic ovarian morphology), were associated with HMGB1 levels." (PMID 37256493, 2023).